ZFP69 (ZFP69 zinc finger protein)
Description:
Putative transcription factor that appears to regulate lipid metabolism.
Synonyms: ZNF642; ZKSCAN23A; FLJ16030; ZFP69A; ZSCAN54A
Tractability: PROTAC: ubiquitination databases record sites on it.
Gene: Protein-coding gene on chromosome 1 (40,477,233 to 40,496,530, forward strand). Ensembl gene ENSG00000187815.
Subcellular location: Nucleus
Subcellular location (Human Protein Atlas): Nucleoplasm
Pathways (Reactome):
Gene expression (Transcription): Generic Transcription Pathway
Gene Ontology:
Molecular function: DNA-binding transcription factor activity, RNA polymerase II-specific; RNA polymerase II transcription regulatory region sequence-specific DNA binding; DNA binding
Biological process: regulation of lipid metabolic process; regulation of transcription by RNA polymerase II; regulation of DNA-templated transcription
Cellular component: nucleus; nuclear lumen
Genetic constraint (gnomAD): Loss-of-function variants: 31 observed, 47.32 expected, observed/expected ratio (o/e) 0.66, 90% interval 0.49 to 0.88. The upper end of that interval is the gene's LOEUF score, 0.88, which puts it in group 3 of 6, group 1 being the genes least tolerant of losing a copy. Missense variants: 548 observed, 665.11 expected, observed/expected ratio (o/e) 0.82, 90% interval 0.77 to 0.88. Synonymous variants: 191 observed, 223.66 expected, observed/expected ratio (o/e) 0.85, 90% interval 0.76 to 0.96.
Homologues: Orthologues: chimpanzee ZFP69 (99% identical), rabbit ZFP69 (88% identical), pig ZFP69 (85% identical), guinea pig ZFP69 (84% identical), mouse Zfp69 (75% identical), rat Zfp69 (68% identical), Drosophila melanogaster CG3281 (23% identical), Drosophila melanogaster CG2712 (21% identical), Drosophila melanogaster Phs (21% identical). Paralogues in human: ZFP69B (70% identical), ZNF582 (36% identical), ZNF805 (36% identical), ZNF554 (36% identical), ZFP90 (36% identical), ZFP37 (36% identical), ZNF266 (36% identical), ZNF599 (35% identical), ZNF25 (35% identical), ZNF614 (35% identical), ZNF264 (35% identical), ZNF619 (35% identical), and 50 more.
Diseases named in the same sentence as ZFP69 in open-access papers:
ZFP69 is named in the same sentence as 11 diseases in open-access papers, as found by Europe PMC text mining. Sharing a sentence is not in itself a finding about the gene and the disease. The quoted sentences say what the papers report.
diabetes (8 papers, 2009 to 2024). "Zfp69 was previously identified by positional cloning as a candidate gene for obesity-associated diabetes." (PMID 26232096, 2015). "The 95% CI for QTLs on chromosomes 1 and 4 contained plausible candidate genes, Ifi202b and Zfp69, respectively, both of which were known to be related with obesity-associated diabetes." (PMID 23641944, 2013). "Redistribution of triglycerides caused by Zfp69 would enhance the deleterious effects of the reduced fat oxidation, and explain the accelerated onset of diabetes observed in the presence of both diabetogenic alleles." (PMID 19578398, 2009). "Zfp69 has been previously suggested to be a causal gene in the diabetes loci Nidd1 and Nidd/SJL." (PMID 26232096, 2015). "Thus, the data are consistent with the conclusion that Zfp69 is a causal gene of the diabetes locus Nidd/SJL." (PMID 26232096, 2015). "Thus, the transcription factor ZFP69/ZNF642 may be involved in the pathogenesis of obesity-associated diabetes." (PMID 19578398, 2009). "For instance, Hddc3 and Zfp69, whose expression is downregulated under light conditions, are involved in ferroptosis and insulin sensitivity during diabetes, respectively." (PMID 38252153, 2024). "Recently, the zinc finger protein 69 (Zfp69) gene was identified as a candidate for the diabetes QTL of Nidd/SJL." (PMID 21167066, 2010). "Based on these data, we expected that SJL, NON, and NZB carry an identical (diabetogenic) allele of Zfp69, and that NZO and B6 both carry a diabetes-suppressing allele." (PMID 19578398, 2009). "Surprisingly, diabetes appears to be produced by ‘rescue’ of a loss-of-function variant of Zfp69: NZO mice and the diabetes-resistant B6 strain express a truncated mRNA, whereas the diabetogenic allele from SJL and NON produces a ‘normal’ expression of Zfp69." (PMID 19578398, 2009). "An allelic variation of Zfp69 was observed in multiple inbred strains; allele carried by B6 and NZO strains causing truncated mRNA was associated with reduced diabetes susceptibility, while allele carried by SJL and NON strains producing normal mRNA was diabetogenic." (PMID 21167066, 2010). "The present data identify the zinc finger domain transcription factor Zfp69 as the most likely candidate for the diabetogenic effect of the mouse QTL Nidd1 and Nidd/SJL which aggravates and accelerates obesity-associated diabetes in the NZO strain, and enhances hyperglycaemia in B6-ob/ob mice." (PMID 19578398, 2009). "However, overexpression of Zfp69 did not induce overt diabetes with hyperglycaemia and beta cell loss." (PMID 26232096, 2015). "By contrast, carriers of the retrotransposon IAPLTR1a in intron 3 of Zfp69 (NZO, C57BL/6J) produce a truncated mRNA and are less diabetes prone (NZO) or fully protected (C57BL6/J)." (PMID 26232096, 2015).
Obesity (6 papers, 2009 to 2021). Accumulation of substantial excess body fat. "We also observe previously identified obesity associated genes, such as Zfp69, Slc24a3, Qpctl, Atp10a, and Folr2." (PMID 22471599, 2012). "Since the diabetogenic effect of the Zfp69 locus required obesity, we challenged control and B6-Tg(Zfp69) mice with a HFD, which markedly increased body weight." (PMID 26232096, 2015). "Zfp69 requires obesity in order to produce hyperglycaemia (‘diabesity’), and needs other diabetogenic alleles in order to produce beta cell failure, hypoinsulinaemia, and weight loss." (PMID 19578398, 2009).
type 2 diabetes (5 papers, 2009 to 2023). "QTL mapping in the NZO mouse has identified Tbc1d1, Zfp69, and Lepr as genes contributing to type 2 diabetes." (PMID 36944993, 2023). "mRNA levels of the human orthologue of Zfp69 and ZNF642 were significantly increased in adipose tissue from patients with type 2 diabetes." (PMID 24752583, 2014). "mRNA levels of the human orthologue of Zfp69, ZNF642, were significantly increased in adipose tissue from patients with type 2 diabetes." (PMID 19578398, 2009). "In humans with type 2 diabetes, mRNA levels of the human orthologue of Zfp69 (ZNF642) were increased in adipose tissue." (PMID 19578398, 2009). "In order to test the possibility that the human orthologue of Zfp69 is involved in the pathogenesis of human type 2 diabetes, we determined its expression in omental and subcutaneous white adipose tissue of diabetic and control individuals." (PMID 19578398, 2009). "However, it does not induce type 2 diabetes, suggesting that the diabetogenic effect of the Zfp69 locus requires synergy with other as yet unidentified genes." (PMID 26232096, 2015).
hyperglycaemia (4 papers, 2009 to 2022). "On the NZO background, the Zfp69 locus caused severe hyperglycaemia and loss of beta cells." (PMID 26232096, 2015). "A possible explanation for the mild phenotype could be that Zfp69 needs other diabetogenic gene variants in order to produce hyperglycaemia and beta cell failure." (PMID 26232096, 2015). "We have identified a gene that appears to be involved in the pathogenesis of hyperglycaemia in obese mice: in some mouse strains, the gene Zfp69 is disrupted by a retroviral transposon (IAPLTR1a), which generates a truncated mRNA." (PMID 19578398, 2009). "Indeed, the contribution of the different mouse strains to hyperglycaemia in the intercross populations corresponded with the allelic variation of Zfp69 in these strains." (PMID 19578398, 2009). "We have previously shown that the introgression of Nidd/SJL encompassing the intact Zfp69 into the NZO background induced hypoinsulinaemia due to beta cell failure, resulting in hyperglycaemia." (PMID 26232096, 2015).
hyperlipidaemia (1 paper, 2015). "Zfp69 mediates hyperlipidaemia, liver fat accumulation and mild insulin resistance." (PMID 26232096, 2015). "Similarly, in a previous study, we observed hepatosteatosis and hyperlipidaemia in recombinant congenic mice carrying the Zfp69 locus of SJL mice and hypothesised that this is due to reduced lipid storage capacity of adipocytes." (PMID 26232096, 2015).
Insulin resistance (1 paper, 2015). Increased resistance towards insulin, that is, diminished effectiveness of insulin in reducing blood glucose levels. "In this study, we present direct evidence in support of this conclusion, and demonstrate that Zfp69 increases liver fat content and plasma triacylglycerol concentrations and causes moderate insulin resistance." (PMID 26232096, 2015). "Glucose clearance during an OGTT at week 18 was not different between B6-WT and B6-Tg(Zfp69) mice, but the insulin concentration was significantly increased in B6-Tg(Zfp69) mice, suggesting that Zfp69 overexpression causes mild insulin resistance." (PMID 26232096, 2015). "As increased hepatosteatosis was shown to correlate with reduced Ppargc1α expression, it can be speculated that lower Ppargc1α levels in the liver of B6-Tg(Zfp69) mice participate in ectopic fat storage and subsequently cause insulin resistance." (PMID 26232096, 2015). "We compared the liver transcriptome of B6-WT and B6-Tg(Zfp69) mice at an early time point (week 8) before insulin resistance occurs in order to exclude secondary effects of insulin resistance and to examine the direct effect of Zfp69 overexpression." (PMID 26232096, 2015). "Zfp69 induced the accumulation of liver fat and a mild insulin resistance, confirming the role of Zfp69 as a diabetogenic gene." (PMID 26232096, 2015).
metabolic disorder (1 paper, 2024). "Notably, the downregulation of Zfp69 is also found in db/db mice, which suggests that metabolic disorder occurs at the onset of retinopathy in the Prom1−/− retina." (PMID 38252153, 2024).
ZFP69 also shares sentences with these, for which no sentence is quoted: Hypoinsulinemia (1 paper); neurological diseases (1); Parkinson disease (1); retinopathy (1).